ETV5 (ETS variant transcription factor 5)
Diseases named in the same sentence as ETV5 in open-access papers (continued):
Sharing a sentence is not in itself a finding about the gene and the disease.
Sertoli Cell-Only Syndrome (2 papers, 2021 to 2024). A type of male infertility in which no germ cells are visible in any of the biopsied SEMINIFEROUS TUBULES (type I) or in which germ cells are present in a minority of tubules (type II). "Our previous studies have shown that ets variant 5 (Etv5) gene knockout in mice results in a blockage of spermatogenesis, leading to Sertoli cell- only syndrome." (PMID 38791636, 2024). "Etv5 encodes a TF with roles in SSC self-renewal and maintenance; its loss causes progressive germ-cell depletion and Sertoli-cell-only syndrome in mice." (PMID 34289349, 2021).
Anxiety (1 paper, 2024). Intense feelings of nervousness, tension, or panic often arise in response to interpersonal stresses. "A reduction in Etv5 protein levels was accompanied by autistic-like, anxiety-like behaviors, and a deficit in spatial memory in Rfwd2+/− male mice." (PMID 38503925, 2024). "It is likely that decreased Etv5 expression in other brain regions contributes to anxiety-like behavior in Rfwd2+/− male mice, so that expression of ETV5 in the mPFC is probably not sufficient to rescue the anxiety deficits." (PMID 38503925, 2024). "In contrast, restoration of ETV5 in the mPFC did not rescue the spatial memory deficits or the anxiety-like behaviors." (PMID 38503925, 2024).
astrocytoma (1 paper, 2019). "The loss of CIC protein in patient-derived samples correlated with de-repression the CIC targets, ETV1 and ETV5, in human GBM and in lower-grade astrocytoma." (PMID 30737375, 2019).
bipolar disorder (1 paper, 2016). A disorder of the brain that causes unusual shifts in mood, energy, activity levels and the ability to carry out day-to-day tasks. "In regions of the human brain linked to bipolar disorder, such as the anterior caudate and mid-frontal lobe, the ETV5-linked SNP rs7433760 mapped to an enhancer specific for those regions." (PMID 27280443, 2016). "Finally, we reveal a human association of ETV5 with bipolar disorder." (PMID 27280443, 2016). "Using the GWAS Central database we searched for ETV5 localized SNPs that had a significant link (P < 0.05) to either BMI or bipolar disorder." (PMID 27280443, 2016).
bladder tumours (1 paper, 2019). "In the FGFR3-mutant MGHU3 and UMUC14 lines, which are derived from less invasive bladder tumours, ETV5 knockdown had a similar effect on reducing cell numbers at confluence, but a less striking effect on colony formation." (PMID 30952872, 2019). "As FGFR3 mutations are more common in low grade and stage bladder tumours, and are an early change during urothelial transformation, it is likely that besides favouring EMT in more advanced tumours, ETV5 may modulate other classes of genes in early neoplastic lesions." (PMID 30952872, 2019). "This confirms a link between ETV5 expression and the level of TAZ and its target genes in bladder tumours." (PMID 30952872, 2019). "To investigate the link between FGFR3, ETV5 and TAZ in vivo we interrogated two large publically available bladder tumour data sets." (PMID 30952872, 2019).
brain tumors (1 paper, 2018). "Using the betweenness centrality measure, we identified Etv5 as a potential tissue-level regulator in murine neurofibromatosis type 1 (Nf1) low-grade brain tumors (optic gliomas)." (PMID 29787563, 2018). "Leveraging the betweenness network analysis and RNA-sequencing of murine optic glioma tissues, we discovered Etv5 and Etv5-associated genes as a differentially-regulated transcriptional network in low-grade brain tumors relative to non-neoplastic brain tissue." (PMID 29787563, 2018).
cardiomyopathies (1 paper, 2023). "In particular, Males Only DMRs selected by machine learning feature selection were able to distinguish CHD from non-CHD samples and frequently mapped to genes associated with CHDs or cardiomyopathies, including FUNDC1, ETV5, SYT9, CAMTA1, GRIA4, and IGF1R." (PMID 37803336, 2023).
cervical cancer (1 paper, 2024). A primary or metastatic malignant neoplasm involving the cervix. "In general, our research showed that ATL III inhibits the migration and invasion of cervical cancer cells by regulating IGF2BP3 through ETV5." (PMID 38358034, 2024). "Finally, we explored the possible role of ETV5 as a transcription factor in the role of ATL III in cervical cancer via IGF2BP3." (PMID 38358034, 2024).
cognitive deficits (1 paper, 2025). "Thus, future efforts will be required to explore the role of Etv5 and other ERK targets in OPC and cognitive deficits in MRR." (PMID 41446112, 2025).
colitis (1 paper, 2025). Inflammation of the colon. "In contrast, silencing TAF1 expression in IL-9-stimulated fibroblasts reduced the expression of Col1a1, Col3a1, collagen I, and collagen III, suggesting that IL-9 interacts with ETV5 and subsequently regulates TAF1, thereby contributing to the production of colitis-associated inflammatory factors." (PMID 40771819, 2025).
ependymoma (1 paper, 2024). A WHO grade II, slow growing tumor of children and young adults, usually located intraventricularly. "The ETS variant transcription factor 5 (ETV5) is one of the key downstream effectors of H3Q5ser in ependymoma and has important roles in both neuronal development and chromatin regulation." (PMID 39115570, 2024).
Hyperglycemia (1 paper, 2021). An increased concentration of glucose in the blood. "Hyperglycemia reciprocally regulates CRL4-CSN versus CRL4COP1 assembly to promote ETV5 degradation." (PMID 33911083, 2021).
Hyperinsulinemia (1 paper, 2021). An increased concentration of insulin in the blood. "To exclude possible HFD-specific effects of MLN4924, we examined the leptin-deficient ob/ob mice, whose uncontrolled food intake elicits hyperinsulinemia and low ETV5 levels under normal diet." (PMID 33911083, 2021).
inflammatory bowel disease (1 paper, 2024). A spectrum of small and large bowel inflammatory diseases of unknown etiology. "The expression of ETV5 in intestinal mucosa and peripheral blood CD4 T cells of inflammatory bowel disease (IBD) patients is significantly increased." (PMID 39337492, 2024).
insulinoma (1 paper, 2021). "Depleting COP1 or DET1 leads to the accumulation of ETV5 and, to a mild extent, ETV4 in MIN6 insulinoma cells, whereas co-expressing COP1 and DET1 diminishes ETV5 levels, suggesting that CRL4COP1/DET1 mediates ETV5 degradation, which is further supported by ETV5 stabilization upon MLN4924 treatment." (PMID 33911083, 2021).
low grade glioma (1 paper, 2018). A grade I or grade II glioma arising from the central nervous system. "Finally, we validated the differential expression of Etv5 in several other Nf1 murine models of optic glioma, as well as in human low-grade glioma (pilocytic astrocytoma, PA) datasets." (PMID 29787563, 2018).
myeloid leukaemia (1 paper, 2023). "Hhex expression, in combination with a mutant form of additional sex combs-like 1 (Asxl1) an epigenetic modulator often mutated in myeloid leukaemia, was also found to enhance Runx1-ETO and Flt3-ITD-driven myeloid leukaemia via upregulation of Myb and Etv5 in mice." (PMID 37398663, 2023).
neuropathy (1 paper, 2016). A disorder affecting the nervous system that manifests with pain, tingling, numbness, and/or muscle weakness. "Importantly, the absence of expression of several embryonic genes in denervated SCs (AP2α, Etv5, Pax3) may provide a strategy to enhance or prolong the repair phenotype to improve recovery of function following PNS injury or neuropathy." (PMID 27058953, 2016).
pancreatic cancer (1 paper, 2020). "Indeed, a prior study suggested that overexpression of a single ETS TF confers resistance to MEKi trametinib in KRAS mutant pancreatic cancer, while suppression of ETV1, ETV4, or ETV5 alone strongly decreased the resistance." (PMID 32413516, 2020).
pancreatitis (1 paper, 2023). Inflammation of the pancreas. "In the model of cerulein induced pancreatitis, mice with conditional knockout of ETV5 exhibit delayed recovery from the inflammation and associate with decreased SOX9 expression in pancreas." (PMID 36872348, 2023). "While, SOX9−/− mice undergo the cerulein induced pancreatitis maintain ETV5 expression." (PMID 36872348, 2023). "In pancreatic ductal cells, the luciferase reporter assay demonstrates that upregulated ETV5 increases the activity of SOX9 promoter, indicating ETV5 might be an upstream regulator of SOX9 during pancreatitis." (PMID 36872348, 2023).
pilocytic astrocytoma (1 paper, 2018). Pilocytic astrocytoma is a rare subtype of low-grade glioma of the central nervous system characterized by a well circumscribed, often cystic, brain tumor with a discrete mural nodule and long, hair-like projections that extend from the neoplastic astrocytes. "We further validated the differential expression of Etv5 and its target genes in several other murine models of Nf1 optic glioma, as well as in human pilocytic astrocytomas." (PMID 29787563, 2018). "As such, the expression of Etv5 and Etv5 target genes were increased in multiple independently-generated mouse optic glioma models relative to non-neoplastic (normal healthy) optic nerves, as well as in the cognate human tumors (pilocytic astrocytoma) relative to normal human brain." (PMID 29787563, 2018).
rectal cancer (1 paper, 2022). A primary or metastatic malignant neoplasm that affects the rectum. "Meanwhile, ETV5 expression had significantly positive correlations with CD8+ T cells (rcoad = 0.326, rread = 0.369), macrophages (rcoad = 0.228, rread = 0.271), DCs (rcoad = 0.342, rread = 0.332), and CAFs (rcoad = 0.286, rread = 0.365) both in colon and rectal cancer." (PMID 35860243, 2022).
renal agenesis (1 paper, 2010). Renal agenesis (RA) is a form of renal tract malformation characterized by the complete absence of development of one or both kidneys (unilateral RA or bilateral RA respectively), accompanied by absent ureter(s). "Loss of Gdnf causes renal agenesis because in the presence of SPRY1 the level of FGF10 signaling via FGFR2 is not sufficient to produce the necessary responses, such as an appropriate level of Etv4 and Etv5 expression." (PMID 20084103, 2010). "When Spry1 is absent there is no brake on signaling via FGFR2, and GDNF can be removed without causing renal agenesis, due (at least in part) to the effects of FGF10, and to the restoration of Etv4/Etv5 expression; however, UB branching pattern is abnormal." (PMID 20084103, 2010). "In contrast to Gdnf or Ret mutations, renal agenesis caused by concomitant lack of the transcription factors ETV4 and ETV5 is not rescued by removing Spry1, consistent with their role downstream of both RET and FGFRs." (PMID 20084103, 2010).
rhabdomyosarcoma (1 paper, 2014). A rare aggressive malignant mesenchymal neoplasm arising from skeletal muscle. "This fusion protein activated transcription of the PEA3 family genes ERM/ETV5 and ETV1 and overexpression of PEA3 family proteins was associated with invasive and metastatic phenotypes in breast and gastric cancers and in rhabdomyosarcoma." (PMID 25277207, 2014).
spinocerebellar ataxia (1 paper, 2019). "ETV5 is also upregulated in a mouse model of spinocerebellar ataxia." (PMID 31037649, 2019).
synovial sarcoma (1 paper, 2023). "For example, ETV5 is overexpressed in synovial sarcoma tumors." (PMID 37876309, 2023). "This suggests a transcriptional regulation of ETV5 on E2F1, but in an opposite direction than the one established in the synovial sarcoma report." (PMID 37876309, 2023).
teratospermia (1 paper, 2017). "The higher number of common up-regulated genes was found between Etv5 KD and Pou3f1 KD, with 53 genes, Bcl6b KD and Etv5 KD, with 19 genes, Bcl6b KD and Pou3f1 KD, with 14 genes, MArrest and teratospermia, with 12 genes, and MArrest and Ing2 KO, with nine common genes." (PMID 29150651, 2017).
ZIKV infection (1 paper, 2018). "In agreement with previous study, the expression of TRA98 and ETV5 was gradually impaired by ZIKV infection." (PMID 29447264, 2018).
tumor (67 papers, 2007 to 2026). "In conclusion, ETV5 was associated with ESCC tumor staging and ESCC prognosis clinically." (PMID 35813298, 2022). "Tumours harbouring RAS/MAPK pathway mutations displayed significantly higher ETV5 expression." (PMID 31937834, 2020). "Together, these results indicate that ETV4 and ETV5 are involved in tumor cell proliferation and are the main mediators of drug resistance upon inactivation of CIC." (PMID 41219537, 2025). "ETV1, ETV4, and ETV5 can enhance the proliferation, migration, and invasion of tumor cells, thereby leading to tumor progression, metastasis, and drug resistance." (PMID 39668941, 2025). "In contrast, the expression levels of ETV4 or ETV5 in GBM are significantly higher compared to non‐tumour samples only in the Rembrandt database." (PMID 40275610, 2025). "We compared the expression levels of ETV1, ETV4 and ETV5 mRNA between the non‐tumour brain samples and GBM samples from the TCGA and Rembrandt databases." (PMID 40275610, 2025). "The overall effects of “degradation and translation conflicts” caused by YTHDF2 resulted in the elevated protein expression of ETV5 and promoted tumor progression." (PMID 38247171, 2024). "A recent study advocated that targeting tumor cell-derived CCL2 seems to be a feasible strategy to overcome bevacizumab resistance in Etv5+ CRC." (PMID 38419056, 2024). "Collectively, these data imply that under the effect of TAOK3's phosphorylation, KMT2C mediates histone methylation and transcriptionally upregulates the expression of IRGM together with ETV5, and tumor autophagy is augmented consequently." (PMID 37705061, 2023). "Based on the gene expression profiles correlated to drug responses, ETV5 was identified as a biomarker of tumor sensitivity to the MEK inhibitors cobimetinib and selumetinib." (PMID 36872348, 2023). "We found that among all ETS family transcription factors, ETV4 and ETV5 consistently demonstrated the highest Pearson correlation coefficient between each other in both the cell line and primary tumor datasets." (PMID 36509998, 2023). "E26 transformation-specific (ETS) transcription factors including ETV5, play important roles in tumor cell invasion, differentiation and angiogenesis." (PMID 36212151, 2022). "FN1, SOX4 and ETV5 were further validated in HNSCC patients’ tumor tissues with irradiated failures, which is novel radioresistance biomarkers in HNSCC." (PMID 36212151, 2022). "In this study, we found that ETV5 was upregulated in ESCC both from online database and our ESCC tissues and ETV5 was associated with tumor staging and prognosis." (PMID 35813298, 2022). "We explored the correlation of ETV1, ETV4, and ETV5 with tumor-infiltrating immune cells (TIICs) in CRC tumor microenvironments via the Tumor Immune Estimation Resource (TIMER) and Gene Expression Profiling Interactive Analysis (GEPIA)." (PMID 35860243, 2022). "Meanwhile, a higher ETV5 IHC score was correlated with the superior tumor dimension (p = 0.022), more positive lymphatic metastasis status (p = 0.032), and higher TNM stage (p = 0.048)." (PMID 35860243, 2022). "Overexpression of FN1, SOX4 and ETV5 were found in 43 paired samples between paracancerous tissues and tumor tissues of HNSCC." (PMID 36212151, 2022). "This study described, for the first time, that ETV5 expression was significantly increased in ESCC tissues and it was associated with ESCC tumor staging and ESCC prognosis clinically." (PMID 35813298, 2022). "In conclusion, ETV5 promoted cell cycle G1/S transition through transcriptional inhibition of p21, thereby accelerating tumor growth." (PMID 33931578, 2021). "In our study, we found that most cancer driver genes are specifically expressed in tumor tissue, and we constructed a four-mRNA prognostic signature (ETV5, EZH2, PABPC1, ZCRB1) that has higher predictive power than other clinical features." (PMID 34335239, 2021). "ETV5 upregulation enhanced tumor proliferative capacity and promoted G1 phase transfer to the S phase." (PMID 33931578, 2021).
tumor (continued). "Here, in vitro and in vivo experiments were performed to verify that ETV5 promoted tumor progression and influenced cell cycle G1/S transition." (PMID 33931578, 2021). "Through in vivo and in vivo experiments, we confirmed that ETV5 upregulation enhanced tumor proliferative capacity." (PMID 33931578, 2021). "ETV5 leads to tumor initiation, progression, and metastasis by governing numerous biological processes, including cell cycle control, differentiation, proliferation, apoptosis, tissue remodeling, and angiogenesis." (PMID 33099574, 2020). "The effect of ETV5 on tumour cell behaviour in vivo was analysed using the previously used SH-SY5Y xenograft tumour model in immunocompromised mice." (PMID 31937834, 2020). "Additional studies, including orthotopic in vivo modelling, are however needed to further investigate and clarify the possible contribution of ETV5 to aggressive tumour cell behaviour." (PMID 31937834, 2020). "These SH-SY5Y cells were transduced with shETV5 to achieve ETV5 knockdown in the xenograft tumours resulting from engraftment." (PMID 31937834, 2020). "Taken together, our data indicate that ETV5 contributes to proliferation, migration, invasion and colony formation, which can, at least partly, explain the contribution to tumour aggressiveness." (PMID 31937834, 2020). "The expression levels of CCL2 were higher in tumor tissues in the RKO/ETV5+Bev group compared to those in the RKO/Vector+Bev group in vivo." (PMID 33099574, 2020). "Xenograft tumours of SH-SY5Y (ALKF1174L) cells from TAE-684-treated mice showed likewise ETV5 mRNA downregulation." (PMID 31937834, 2020). "The resulting ETV5 knockdown in vivo reduced tumour volume over time compared to tumours originating from the control SH-SY5Y cells." (PMID 31937834, 2020). "For instance, overexpression of ETV4, ELF3, and ETV5 facilitates tumor angiogenesis, growth, invasion and metastasis, and indicates poor prognosis." (PMID 33585247, 2020). "In other tumour types, ETV5 has been found to mediate EMT through modulation of invasion-related genes, such as NID1, MMP2 and FOXM130,53,54." (PMID 30952872, 2019). "Collectively, these results validate the tumor-specific expression of Etv5 at both the RNA and protein levels." (PMID 29787563, 2018). "To extend the in silico findings, and to validate Etv5 as a differentially-expressed tumor-specific gene, we performed a series of complementary experiments." (PMID 29787563, 2018). "As expected, the tumors generated by the ETV5-overexpressing cells presented larger myometrial invasion and tumor burden." (PMID 29682175, 2018). "Other than ERG fusions, we observed nine tumors with ETV1 rearrangements (10%) and 1 tumor with an ETV5 fusion transcript (1%)." (PMID 30464211, 2018). "The present study suggests that Etv4 and Etv5 play an important role in tumor progression by altering chromatin accessibility and gene expression during EMT." (PMID 28446749, 2017). "There fore, dysregulation of ETV5 (by DNA methylation) would lead to increase invasive potential of tumor cells." (PMID 19455234, 2007). "Restoring CIC repressor activity or silencing of its target genes Etv4 and Etv5 decreases resistance to MAPK pathway inhibition, similar to treatment with drugs (PFK15 and Tx-1123) that selectively affect the viability of Cic-deficient tumor cells." (PMID 41219537, 2025). "Precancerous clusters showed enrichment in tumor progression-related regulons, including transcription factors (TFs) linked to tumor proliferation and cell cycle progression (STAT1, BCL6, ETV5) and potential tumor suppressors (ELF5, LTF, RXRG, CEBPD), as well as EMT-related regulons." (PMID 39872221, 2025). "Moreover, the expression of putative Stat3 target genes Abca3 and Etv5 significantly decreased in Stattic-treated KPY tumor organoid cells compared to DMSO treatment (Fig. EV2I)." (PMID 39930268, 2025). "Indeed, the well-known CIC targets ETV4 and ETV5 are key mediators of tumor cell proliferation and drug resistance." (PMID 41219537, 2025).